CD44 (CD44 molecule (IN blood group))
Diseases named in the same sentence as CD44 in open-access papers (continued):
Sharing a sentence is not in itself a finding about the gene and the disease.
glioma (continued). "Consistent with the idea that this metabolic activity may be driven by mesenchymal glioma cells enriched in SXO210 explants, the UTSW63, TS516, and HK157 GSC lines expressed low or undetectable levels of the mesenchymal marker CD44." (PMID 37398280, 2025). "Generally, these results suggested that ANXA5, STAT1, CD44, CAV1, MAPT, and ANXA2 might play a critical role in the pathogenesis of glioma, suggesting that the hub genes might be a promising biomarker of glioma." (PMID 40607003, 2025). "Altogether, these findings suggested that ANXA5, STAT1, CD44, CAV1, MAPT, and ANXA2 might play a vital role in the pathogenesis of gliomas." (PMID 40607003, 2025). "Notably, the protein expression level of CD44 in grade II and III gliomas is higher than that in normal brain tissue but lower than that in glioblastoma grade IV tissue." (PMID 38672482, 2024). "The MIF signals sent by glioma cells (Clusters C1, C2 and C4) were mainly received by TAMs (Cluster C0) via receptors CD74 and CXCR4, and by lymphocytes (Cluster C6) via CD74, CXCR4 and CD44." (PMID 38515213, 2024). "Additionally, Shikonin treatments resulted in diminished levels of glioma stem cell markers (SOX2, CD44, CHI3L1, and CD24) and the BMDM-derived TAM marker CD49D in glioma cells and subcutaneous animal models." (PMID 39619148, 2024). "Additionally, glioma cluster 2 cells expressed selectins (LGALS1 and LGALS3), integrins (ITGB1), and glycosylation targets (VIM, TIMP1, HIF1A, and CD44)." (PMID 39333557, 2024). "Through binding with CD44, OPN promotes the stemness phenotype and chemoresistance in glioma." (PMID 38334650, 2024). "PTK7 regulates Id1 expression to promote cell proliferation and tumorigenesis, inhibit apoptosis of CD44-high gliomas, and induce anchorage-independent growth of normal astrocytes through the TGF-β/Smad signaling." (PMID 39474113, 2024). "Consequently, we found an increase in the expression of GFAP, but a decrease in the expression of Nestin and two markers of glioma stem cells, CD133 and CD44, indicating that low expression of OGDH promotes glioma cell differentiation." (PMID 39872214, 2024). "The IDH1 mutation impeded the maturation of astrocytes with low OGDH, but we found that it did not alter the expression of GFAP, Nestin, CD133, and CD44 in U87 and U251 glioma cells." (PMID 39872214, 2024). "Moreover, follow‐up experiments identified the inhibition of orthotopic glioma growth by AS1411 aptamer coloading shikonin and docetaxel targeting CD44‐overexpressing glioma." (PMID 38783892, 2024). "Our previous study confirmed that the expression of hyaluronan synthase 3 (HAS3) and CD44 is elevated in gliomas; on the one hand, increased HAS3 expression can promote HA biosynthesis, and on the other hand, overexpressed CD44 can combine with HA to accelerate glioma progression." (PMID 37568202, 2023). "Importantly, we found a positive correlation between A3C and glioma stem cell marker genes such as CD133, SOX2, Notch3, CD44, and CXCR4 was noted." (PMID 37809064, 2023). "Here, we demonstrate that myeloid-specific but neither astrocyte- nor endothelial-specific CD44 deletion significantly affected glioma invasiveness in organotypic brain slices." (PMID 35992852, 2022). "Interestingly, absence of CD44 similarly affected three human cell lines as well as primary human and murine glioma cells, implying that TME-CD44-dependant invasion is a mechanism shared by various mouse and human cell models." (PMID 35992852, 2022). "The upregulation of CD44 is insufficient to definitively conclude that sevoflurane does not affect the stemness of human glioma stem cells." (PMID 36363571, 2022). "Ultimately, we speculate that CDCP1, CD44 and ITGAM can be used to better diagnose glioma and predict the prognosis of glioma patients." (PMID 35410293, 2022). "Further qRT-PCR analysis revealed that in the presence of glioma cells, WT but not CD44-/- microglia notably increased mRNA levels of TNF-α." (PMID 35992852, 2022).
glioma (continued). "By dividing the invasion area of spheroid cells to spheroid size, we found that CD44 deletion in either astrocytes or in endothelial cells does not affect glioma migration." (PMID 35992852, 2022). "We have analyzed U251MG glioma cells, expressing CD44 or not, and grown in stem cell-like enriched spheres." (PMID 35954411, 2022). "Using an ex-vivo organotypic brain slice invasion assay, we show that absence of CD44 from the TME impairs the ability of glioma cells to invade the surrounding brain parenchyma." (PMID 35992852, 2022). "Considering its increased levels correlating with glioma grade and malignancy and given its broad expression pattern within the TME, we considered CD44 to be an interesting target to investigate in the context of tumor-host interactions affecting glioma invasion." (PMID 35992852, 2022). "While our results demonstrate a disrupted pro-tumorigenic profile of CD44-/- microglia in response to glioma cells, it appears that in vivo, these alterations are not sufficient to significantly affect glioma invasion or increase survival." (PMID 35992852, 2022). "Importantly, we also observed a significant correlation between CD44 and VIM expression in glioma samples." (PMID 34805184, 2021). "These hub genes correlated with CD44 are involved in immune response (e.g., macrophage activation, cytokine production, microglial cell activation, and T cell activation) in both TCGA and CGGA glioma datasets." (PMID 35187044, 2021). "Furthermore, we confirmed the strong expression of CD44, OPN and VIMENTIN in this glioma by immunohistochemical analysis." (PMID 34805184, 2021). "In glioma, CD44 and integrins attach the cell to ECM forming focal adhesion complexes and generate traction forces that facilitate cell spreading, essential in the cell migratory machinery in glioma cell invasion." (PMID 34409033, 2021). "In addition, to elucidate the roles of CD44 in anti‐VEGF therapy, we performed in vitro and in vivo studies using glioma stem‐like cells (GSCs) and a GSC‐transplanted mouse xenograft model, respectively." (PMID 33543833, 2021). "We provided a single-cell atlas of the cellular components in this tumor, and revealed essential roles of tumor-immune cell interactions in promoting glioma progression, such as the crosstalk between macrophages and tumor cells mediated by SPP1/CD44 interaction." (PMID 34805184, 2021). "One possible explanation is that HAS3 and CD44 are already highly expressed in gliomas, and therefore, increasing their expression has no obvious effect on glioma proliferation." (PMID 33986244, 2021). "Our results only indicate that HA can play a role through CD44, but it does not deny the biological role of CD44 on glioma cells through HA-independent pathways, which is also a goal of our future research." (PMID 33986244, 2021). "To identify the prime candidate miRNAs controlling the CD44 mRNA’s fate in glioma-derived tumor cell models and primary GBM, we analyzed the expression of miRNAs, which are predicted by TargetScan to target the CD44-3′UTR, by using small RNA-seq derived from cell models or publicly available data." (PMID 33291443, 2020). "The authors performed meta-analyses to study the prognostic significance of CD44 in gliomas, and drew the conclusion that high expression of CD44 may predict poor survival in glioma, particularly in WHO grade II–III gliomas." (PMID 33030522, 2020). "Moreover, the protein levels of CD44, β-catenin, N-cadherin, Vimentin, and MMP14 were also decreased in miR-124-3p overexpressing glioma cells and increased in miR-124-3p deprived cells." (PMID 32127518, 2020). "According to survival analysis, grade II/III glioma patients with high mRNA expression of CD44 experienced poor overall survival (OS) and progression-free survival (PFS) in comparison with low mRNA level of CD44 in an independent manner." (PMID 33303029, 2020).
glioma (continued). "We also evaluated the expression levels of the epithelial marker E- cadherin, N-cadherin, SNAI2, CD44, and vimentin in treated U87 and U251 cells to examine whether EMT is regulated by ZBC260 in glioma cells." (PMID 33093476, 2020). "In conclusion, results of meta-analysis showed that higher tumor expression of CD44 may predict poor survival in patients with glioma, particularly in those with WHO stage II–III glioma." (PMID 32232385, 2020). "In U87 glioma cell, suppression of LICN01503 could significantly inhibit the expression of CD44, but increase OLIG2 expression, suggestive of mesenchymal-to-proneural transition." (PMID 33028341, 2020). "Specifically, higher tumor CD44 expression significantly predicted poor OS in patients with WHO stages II–III glioma (HR: 2.99, 95% CI: 1.53–5.89, P=0.002; I2=0%), but not in patients with glioblastoma (HR: 1.26, 95% CI: 0.76–2.08, P=0.47; I2=55%)." (PMID 32232385, 2020). "Strikingly, MSI1 is co-expressed with CD44 in single neoplastic cells at the invasive front of GBMs, supporting the view that MSI1′s role in promoting stem cell properties in gliomas essentially relies on the impairment of miRNA-directed downregulation of stem cell markers like CD44." (PMID 33291443, 2020). "In summary, in this meta-analysis, HRs of CD44 in grade II–III gliomas should not be combined with that in grade IV gliomas." (PMID 33030522, 2020). "We infected U87MG glioma cells with pLKO.1-puro lentiviruses carrying a negative-control shRNA or two different sequences of short hairpin RNA (shRNA) against human CD44." (PMID 32977522, 2020). "Of them, 14 studies were further excluded; four were preclinical studies, two did not include patients with glioma, four did not report the outcome of OS, three did not measure tumor expression of CD44, and one was a repeated report of an included study." (PMID 32232385, 2020). "In glioma, the CD133(+) or CD44(high)/Id1(high) fractions are recognized as CSCs." (PMID 29907133, 2018). "The isolation and characterization of glioma CSCs is complicated by the absence of universal phenotypic markers, but a number of candidate proteins have been proposed for its role: СD133, CD44, CD49f, Musashi-1, Nestin, Nanog, Oct4 and Sox2." (PMID 31435515, 2018). "Several CSC markers have been reported in glioma, such as CD133, CD24, CD90, CD44 and EpCAM." (PMID 30208924, 2018). "On the other hand, the expression of miR-34a is lower in glioma compared to normal brain tissue and in CD44+-enriched glioma cell lines compared with nontumorigenic neural stem cells." (PMID 29259986, 2017). "In the present study, we focused our attention on different putative negative prognostic markers of GBM linked with GSC or GIC (glioma initiating cells): CD133, CD90 and CD44." (PMID 29348889, 2017). "Our finding suggested that stimulating the Wnt/β-catenin signaling pathway could reduce the cell invasion of glioma cells by inhibiting the gene expression of Col1A1, LAMC3, and CD44." (PMID 28837560, 2017). "In addition, hyaluronic acid, which is a glycosaminoglycan that binds to cell surface CD44, also induces MMP-9 expression in glioma cells via activation of the FAK signaling pathway." (PMID 27602495, 2016). "In gliomas, glioma stem cells (GSCs) were described and have been analyzed based on their expression of “stem-cell markers” such as CD133, CD15, and CD44 or their phenotype of “side population” as evaluated by flow cytometry, but there has been no consensus on the marker phenotypes of GSCs." (PMID 26799577, 2016). "Additionally, the expression of CD44, a receptor for hyaluronic acid and further ligands, e.g. CCL5 was determined at comparable protein levels in glioma cells and melanoma cells." (PMID 26796342, 2016). "There are early suggestions that in some systems, notably glioma and colon cancer, OPN may promote stem-cell like changes through triggering expression and signaling of its cell surface receptor CD44." (PMID 26821678, 2016).
glioma (continued). "Compared to CD133, CD44 is identified as a classic CSC marker and widely presents in various cancers including breast, stomach, glioma, colon, head and neck cancers, while CD133 mainly express in glioma, neural tumors and liver cancer." (PMID 26540347, 2015). "In addition, genetic modulation of KITENIN altered the expression of several factors related to glioma stemness, including CD133, CD44, ALDH1, and EPH-B1." (PMID 25605251, 2015). "Additionally, CD44 ligation induces caspase-independent cell death via a novel calpain/AIF pathway in human erythroleukemia cells and U87MG human gliomas." (PMID 26132406, 2015). "Flow cytometric analysis of cell membrane markers revealed that U-251MG, U-251-4q12 and U-251N cells express a uniform high level of classical glioma cell markers such as CD44, CD56, CD90, and CD29 (not shown)." (PMID 24810477, 2014). "Firstly, our data shows that direct targeting of proteins such as CD44, CHI3L1 or PARD3 may be ineffective at this stage of disease as they are already downregulated in glioma cells at the AOI." (PMID 25365423, 2014). "Western blot analysis showed no significant change in expression of either moesin or CD44 in glioma cells (U87 / U373) on treatment with HA." (PMID 23855374, 2013). "However, the OG cells abundantly express the mesenchymal markers CD44, BCL2A1, Wilms Tumor 1, similar to the recently described transitional glioma phenotype." (PMID 24278309, 2013). "By flow cytometry, the IL13Rα2-positive glioma cell lines (PBT015, PBT017-4, PBT030, PBT036, U251T) generally express higher levels of the mesenchymal adhesion markers CD44 and CD54/ICAM-1 than the IL13Rα2-negative glioma lines (PBT003-4, PBT008, PBT009, PBT022)." (PMID 24204956, 2013). "Our data clearly demonstrate that CD44 and CD155 play important roles in glioma cell invasion." (PMID 22363471, 2012). "Joint CD44/CD155 approaches may, however, merit further study in therapeutic targeting of infiltrating glioma cells." (PMID 22363471, 2012). "However, the underlying mechanisms of those phenomena and the possible relationship between CD44 and CD155 in glioma cell invasion have remained unclear." (PMID 22363471, 2012). "In addition, CD44 expression is related to the ability of macrophages (of the M1 phenotype) to infiltrate glioma through interaction with OPN signaling, suggesting an important role of this glycoprotein also in the dynamics of glioma progression." (PMID 40943148, 2025). "To test the effect of KD on the pro-inflammatory transcriptional profile of glioma cells, we sorted Luc+-GL261 cells from mouse brains and found that none of the tested genes were modulated, while others, such as Serping1, H2-T23, and CD44 were under the limit of detection." (PMID 39921723, 2025). "Notably, the p38 MAPK inhibitor (SB203580) significantly decreased the protein expression levels of CD44 in U251 and SHG44 cells with inhibition of p38 phosphorylation, indicating that p38 MAPK was the upstream that governed the CD44 levels in glioma cells." (PMID 40607003, 2025). "Also, HSP47 can stimulate glioma stem cell (GSC) stemness survival by upregulating angiogenesis and ECM restructuring genes (CD44, LAMC1m, Col4A2, ITGB1, FN1, and MMP9) for GSC reactivation, migration, and invasion through a TGF-β and CD44 signaling pathway." (PMID 38994941, 2024). "Notably, adding CHIR99021 (10 μm, for 3 days) to the control medium significantly induced β‐catenin and Met expression in glioma cells but did not affect the expression of c‐Myc, cyclin D1 and CD44 (data not shown)." (PMID 37410396, 2023). "Similarly, analysis in 1p/19q non-codeletion pan-glioma showed up-expressed levels of CD44, which can predict the poor survival of glioma." (PMID 36776876, 2023). "The overexpression of CD44 has been verified to correlate with cancer aggressiveness and migration, while the clinical and immune features of CD44 expression have not yet been thoroughly characterized in gliomas." (PMID 36776876, 2023).
glioma (continued). "In addition, we explored the CGGA, an independent glioma database, and validated expressions of the CCNB1/CDC42/MAPK7/CD44 gene signatures in WHO grade II, III, and IV GBM tumors using the Analysis of variance (ANOVA), with p < 0.05 considered statistically significant." (PMID 35008426, 2022). "Given the experimental setting using transwell units, we hypothesize that glioma invasion-promoting factors secreted by microglia are not produced or released in the absence of CD44." (PMID 35992852, 2022). "Although all over-expressed antigens might not be strong immunotherapeutic targets, certain other types of overexpressed antigens have been studied, such as ALDH1A1 and hTERT in CD44+ breast cancer CSCs, HER2 proto-oncogene in glioma CSCs, and CEP55 and COA-1 in colon CSCs." (PMID 36627890, 2022). "Furthermore, we identified CD44 as a crucial chondroitin sulfate proteoglycan (CSPG) that was modified by CHSY1 on glioma cells, and the suppression of CS formation on CD44 by silencing the CHSY1-inhibited interaction between CD44 and integrin β1 on the adhesion complex." (PMID 34944101, 2021). "In addition, the addition of exogenous HA also partially reversed the decline in cell viability caused by low concentrations (3 μg/ml) of the CD44 antibody, but did not reverse the effect of high concentrations of the CD44 antibody (6 μg/ml) in glioma cells." (PMID 33986244, 2021). "In this context, the failure to detect integrin β1 in the CD44 immunoprecipitation assay may be attributed to the fact that the detergent-resistant lipid raft proteins were not enriched from cultured glioma cells in the present study." (PMID 34944101, 2021). "CD44 is a cell membrane glycoprotein which involved in diverse tumor aggressive processes including invasion, proliferation, apoptosis, and angiogenesis, but there are no studies reporting its activity in glioma immunity." (PMID 35187044, 2021). "Similarly, MT1-MMP, a membrane matrix collagenase, mediated CD44 cell surface cleavage through MEK/ERK and RhoA/ROK pathways, inducing detachment of the cell from the HA substrate and promoting the invasive potential of glioma cells." (PMID 33744285, 2021). "In order to further interrogate glioma stem-cell treatment susceptibility we utilised FACS to isolate four cell subpopulations—CD133-single positive, CD44-single positive, CD133-CD44-double positive and CD133-CD44-double negative." (PMID 34066147, 2021). "Furthermore, we uncovered up expression of CD44 after glioma recurrence in GBM, wild-type IDH, IDH mutation, and 1p19q non-codeletion state in CGGA glioma dataset." (PMID 35187044, 2021). "In order to verify our hypothesis, we found that knockdown of lncRNA TMEM161B-AS1 inhibited the proliferation, migration, invasion of glioma cells, and promoted apoptosis and ferroptosis by down-regulating the expression of FANCD2 and CD44 through sponging hsa-miR-27a-3p." (PMID 34689169, 2021). "CD44, a tumor stem cell biomarker, is upregulated in LGG, and four CD44-related genes with the prognostic value may become prognostic markers and therapeutic targets for low-grade gliomas." (PMID 33381460, 2020). "However, there is no consensus on the relationship between CD44 expression and prognosis in glioma patients." (PMID 33381460, 2020). "Specifically, the predictive efficacy of higher CD44 tumor expression for poor OS may be significant in patients with WHO stage II–III glioma, but not for those with glioblastoma (WHO stage IV)." (PMID 32232385, 2020). "Our subgroup analysis showed that the predictive efficacy of higher CD44 tumor expression for poor OS may be significant in patients with WHO stage II–III glioma, but not for those with glioblastoma." (PMID 32232385, 2020). "Furthermore, CD44-induced EMT and angiogenesis processes may be the therapeutic targets of galangin in glioma." (PMID 31528214, 2019). "Therefore, glioma CSCs and NSCs share markers such as CD133, CD44, CD15." (PMID 31661894, 2019).